YAP1 (Yes1 associated transcriptional regulator)
Diseases named in the same sentence as YAP1 in open-access papers (continued):
Sharing a sentence is not in itself a finding about the gene and the disease.
cancer (continued). "The nuclear transduction of YAP1 is induced by ECM stiffness to increase anoikis resistance and cancer progression." (PMID 40977060, 2025). "Activation of the YAP1/TAZ pathway promotes cell proliferation, cancer stem cell functions, and EMT." (PMID 40813762, 2025). "The YAP1/ABHD11‐AS1/STAU2/ZYX/p‐YAP1 pathway is a useful entry point for exploration of specific mechanisms of mechanical signal conduction from the ECM in ICC cells and their impact on cancer progression." (PMID 39703167, 2025). "High nuclear YAP1 and TAZ levels correlate with poor differentiation, advanced stage, and worse survival in cancers." (PMID 40895190, 2025). "Overexpression of TRIM44 and downregulation of Hippo-YAP1/TAZ can reduce E-cadherin and inhibit the malignant behavior of cancer cells, such as proliferation." (PMID 40061926, 2025). "We and others have reported that JQ1/SAHA (or other HDACi) combination treatment inhibits Yap1 expression in UPS and other cancers." (PMID 38652549, 2024). "Cytoplasmic expression of YAP1 was low in the basal cells of the normal epithelium, dysplastic cells of OED, and cancer cells." (PMID 38444414, 2024). "Pan-cancer analysis revealed that HER2 and YAP1 are highly essential genes (gene effect score < -1) for GC." (PMID 38782859, 2024). "Gem treatment increased cancer cell nuclear Yap1, CXCL5, and fibroblast Cox2 in KPC tumors, while 14-3-3ζ knockout diminished Gem-induced nuclear Yap1, CXCL5, and Cox2 expression." (PMID 39468013, 2024). "Several tools are available to characterize the disruption of YAP1/TAZ-TEAD binding and its use for cancer treatment, including dominant-negative proteins, peptides that block YAP1-TEAD interactions, and drugs that inhibit TEAD activity." (PMID 39502361, 2024). "Tissue homeostasis and development depend on canonical pathways via these signaling core components (YAP1 and TAZ), whereas aberrant signaling has been accompanied by several diseases, including cancer." (PMID 38730733, 2024). "YAP1 is a transcriptional coactivator of TEAD-mediated transcription and a well-established oncogene; its increased activity has been reported in human cancers." (PMID 39345743, 2024). "Genetic aberrations in different Hippo pathway proteins, and YAP1 and TAZ gene amplifications have been identified in numerous cancer types including lung, gastric, and gynaecological cancers, melanoma, and head and neck squamous carcinomas." (PMID 37957015, 2024). "The correlation between YAP1 and BRD4 protein was obtained using Spearman correlation test across 33 cancer types." (PMID 38169595, 2024). "It mentions that factors like Cadherin 1 and integrin subunits α6 and β4 protect against ferroptosis, while the activation of the Hippo pathway (involving YAP1 and WWTR1/TAZ) promotes ferroptosis in cancer cells." (PMID 38369484, 2024). "In cancer cells, the methylation of the RASSF1A promoter triggers a sequence of events where increased expression of nuclear YAP1 and P4HA2 leads to enhanced collagen deposition in the ECM, thereby contributing to its increased stiffness." (PMID 38693104, 2024). "Wnt5a has been reported to induce EMT and cancer stem cells in OC via the TGF-β1/Smad2/3 and Hippo-YAP1/TAZ-TEAD pathways." (PMID 38191909, 2024). "In a short-term assay, combining osimertinib with the K-975 TEAD inhibitor (at a single dose shown to disrupt YAP1/WWTR1 and TEAD binding) resulted in a dose-dependent and significant decrease in persister cancer cells." (PMID 38658677, 2024). "On the other hand, upon YAP1/TAZ activation, genes within the Wnt signaling pathway were suppressed in the RE cells, which is similar to the changes in YAP1-dependent reprogramming of LGR5+ stem cells during intestinal regeneration and cancer." (PMID 38540020, 2024). "For instance, YAP1 signaling has been correlated with drug efflux through breast cancer resistance protein (BCRP) and cancer cell stemness through CD133." (PMID 39456533, 2024).
cancer (continued). "In YK-4C, 4D cases, cancer cells more frequently showed high expression of MST2 (p = 0.0169) and YAP1 (p < 0.0001), as compared to YK-1–3 cases." (PMID 38444414, 2024). "Although TCGA and GTEx database analysis revealed a significant correlation between NF1 and YAP1 in a variety of digestive tract-related malignancies, the role of NF1 in promoting or suppressing cancer in other solid tumors remains undetermined." (PMID 37147639, 2023). "Additionally, the proto‐oncogene MYCN was upregulated together with SOX2 and YAP1, both markers for stem cell self‐renewal, reprogramming and homeostasis, as well as mechanistically promoting proliferation, survival, invasion/metastasis, cancer stemness and drug resistance." (PMID 36819185, 2023). "YAP1 targets play critical roles in EMT and cancer metastasis by remodeling the microenvironment and inducing an aggressive phenotype in cancer cells." (PMID 36936987, 2023). "RBM3, a well-proven oncoprotein in a variety of cancers, promotes the proliferation of HCC cells by increasing YAP1 expression." (PMID 37301543, 2023). "We showed in this study that LINC02159 upregulated YAP1 expression by stabilizing its mRNA through ALYREF-mediated m5C modification, which represents a new mechanism for the regulation of YAP1 in cancer." (PMID 37537569, 2023). "In general, other YAP1- and WWTR1-silenced cancers typically grow in suspension, while YAP1- and WWTR1-expressing cancers grow adherently." (PMID 36719743, 2023). "Consistent with our findings, most studies provide compelling evidence that YAP-1 is highly expressed in SCC from various body sites, and it plays a role in the development and progression of this cancer." (PMID 37476371, 2023). "In this study, we demonstrate that CMA controls the levels of YAP1 and IL6ST, expanding the range of cancer-relevant proteins whose turnover is controlled by CMA." (PMID 35435804, 2023). "Consistent with links between the blue module and cancer, we find that many blue module hub genes, such as Moesin (MSN), YAP1, TEAD1, and WWTR1 are well known for their role in cancer and mediate the EMT." (PMID 36879821, 2023). "Expression of YAP1 and WWTR1 in YAP1- and WWTR1-silenced cancers, including NEhi SCLC, can suppress proliferation." (PMID 36719743, 2023). "Studies have shown that PVT1 participates in multiple signaling pathways in cancer stemness, including the STAT3, PI3K/AKT, YAP1, and TGFβ pathways." (PMID 36894542, 2023). "The positive expression rates of Ezrin, YAP1, and CTGF in cancer tissues were 86.7, 91.6, and 88.3%, while corresponding adjacent tissues showed low expression rates of 23.3, 11.7, and 18.3%, respectively." (PMID 37791063, 2023). "The YAP1-signaling is deeply involved in the biology of TNBC and is considered a vulnerability of this cancer subtype." (PMID 37770435, 2023). "Several m5C-modified mRNAs have been identified as the targets of ALYREF in cancers, such as LRRC8A, Myc, PKM2, and YAP1, among others." (PMID 37537569, 2023). "The most toxic peptide (Saha-CATH5) also suppressed the ERBB and YAP1/TAZ signaling pathways, both of which have been identified as important drivers of cancer proliferation." (PMID 37542170, 2023). "For example, phosphorylation of YAP1 by the YES is necessary for survival and tumorigenesis β-catenin-driven cancers, which are sensitive to the SRC inhibitor Dasatinib." (PMID 36633714, 2023). "Although AMOT is an upstream co‐activator of YAP1, YAP1 binds to the enhancer of AMOT and induces its expression in human cancer cells, suggesting a possible feedback control." (PMID 36775869, 2023). "Therefore, targeting YAP-1 may be a potential cancer prevention and treatment strategy." (PMID 37476371, 2023). "YAP-1 is a transcriptional co-activator that, through dysregulation of the Hippo-YAP pathway, has a role in cancer genesis and progression." (PMID 37476371, 2023). "Following co-culture for 48 h, the levels of YAP1 and its target CYR61 were determined in cancer cells." (PMID 36936987, 2023).
cancer (continued). "Overall, the Hippo signaling pathway and its relationship to YAP1 and NRF2 are essential areas of research with significant implications for various fields, including embryonic development, cancer, and organ size regulation." (PMID 37111146, 2023). "Together with YAP1 several EMT-TFs (ZEB1, ZEB2, TWIST2) are upregulated in cancer cells after contact with fibroblasts." (PMID 36936987, 2023). "When YAP1 is phosphorylated by YES1, this complex enters the nucleus and localizes to the promoters of anti-apoptotic genes, driving cancer transformation and survival." (PMID 36532767, 2022). "In other words, a YAP1-IGF-1R signaling loop exists that plays a role in the sorafenib resistance and cancer stemness of HCC." (PMID 35672802, 2022). "Finally, we identified five key EMT pathways dysregulated in CF cells and several proteins among the F508del-CFTR–specific YAP1 interactors, which emerge as major hubs possibly mediating the crosstalk among these pathways and appearing as potential therapeutic targets for both CF and cancer." (PMID 35500936, 2022). "CA3 treatment (1 μM; 48 h) in PC cells reduced the protein expression levels of PAF1, YAP1, TEAD4, CD133 (cancer stem cell marker), and SOX9 (pancreatic ductal marker)." (PMID 36180487, 2022). "Among the oncogenic drivers activated by GPCR, YAP1 plays a pivotal role in the progression and metastasis of CRC, linking with worse prognosis of cancer patients." (PMID 36210463, 2022). "We evaluated the strong correlation of CDH6, YAP1, and OCT4 expression within solid tumors by analyzing 56 clinical cancer cohorts from Oncomine and TCGA databases." (PMID 35356283, 2022). "First, we downloaded the bulk expression data for 50 SCLC cell lines from the Cancer Cell Line Encyclopedia (CCLE) and categorized them according to the key TFs ASCL1, NEUROD1, POU2F3 and YAP1." (PMID 36195615, 2022). "We observed decreased expression of YAP1, WWTR1, CTGF and CYR61 in Cancer Luminal type A/B cells when compared with normal mature luminal cells." (PMID 35217640, 2022). "The cancer-related GSTM1, YAP1 and TGM2 genes showed most significant correlation with expression among the FA-HNSCC amplified genes." (PMID 34997070, 2022). "When Wnt signaling is activated, YAP1/TAZ are released from the complex and accumulate in the nucleus to activate oncogenic pathways for cancer progression." (PMID 35672802, 2022). "Following absorption by cancer cells, miR-92 targets large tumor suppressor kinase 2 (LATS2), which interacts with YAP1 and promotes the nuclear translocation of YAP1 in BC cells." (PMID 36499561, 2022). "Second, differential levels of YAP1 and TAZ expression in the same cancer type suggest their discrete functions during cancer progression through both shared and unique mechanisms of regulation." (PMID 35930163, 2022). "Recent research showed that miR-375 is strongly downregulated in a wide range of cancers and that it suppresses carcinogenesis by targeting various critical oncogenes including AEG-1, YAP1, IGF1R, and PDK1." (PMID 36157234, 2022). "As demonstrated by us and others, the Hippo/YAP1 pathway plays an essential role in GAC progression, cancer stem cell (CSC) attributes, and PC formation." (PMID 35996148, 2022). "In most cancer types, CD274 (PD-L1), NRP1, and TNFSF15 were positively correlated with YAP1 expression." (PMID 36479120, 2022). "Cancer-developing conditions such as chemoresistance, invasion, metastasis, migration, cancer stemness, and EMT can be regulated by Yes-related protein 1 (YAP1) transcription factor." (PMID 35715800, 2022). "We therefore wondered if YAP1, like REST, can also modulate cell fate decisions in PNECs in non-cancer contexts." (PMID 35577801, 2022). "Among them, the relationship between YAP1 and infiltration of CD8+ T lymphocytes, MDSCs, and CAFs has been reported in several cancer types." (PMID 36479120, 2022).
cancer (continued). "YAP1 activation correlates with the clinical stage of HPV infection, and YAP1 localizes to the nucleus in HPV-positive cancers." (PMID 35170430, 2022). "EPIC and TIMER programs showed an opposite correlation between YAP1 expression and infiltration of CD4+ T cells in a few cancer types." (PMID 36479120, 2022). "In this comparison, we also saw YAP1, which was discussed earlier, and MB21D2, whose overexpression facilitates cell proliferation and invasion in cancer, while its suppression leads to apoptosis." (PMID 34941772, 2021). "As a result of this study, it is statistically significant that positive YAP1 expression can negatively impact OS and disease-free survival (DFS) in patients with cancer." (PMID 34953494, 2021). "We integrated YAP1 and PKM coexpression genes in the Cancer Cell Line Encyclopedia (CCLE) dataset and separately defined them as the YAP1 and PKM signature." (PMID 34345207, 2021). "The essential role of the Hippo pathway and YAP1 in various types of epithelial tumors is well established, and YAP is amplified in many human cancers." (PMID 33830081, 2021). "The ‘Gene_Corr’ function (in the ‘Cancer Exploration’ section) was used to compare WNT5A (‘Interested Gene’) and YAP1 (‘Gene Expression’)." (PMID 33643710, 2021). "The clinical and correlation analysis of primary gastric cancer showed that miR-375 targeted the three components of the Hippo pathway, YAP1, TEAD4, and connective tissue growth factor (CTGF), to exert an anti-cancer effect." (PMID 34494089, 2021). "Expression of cancer stem cell markers (CD44, ALDH1, CD133 and YAP1) and activation of oncogenes varied among the cell lines." (PMID 34162421, 2021). "Mechanistically, CYGB‐overexpressing cancer cells were more sensitive to ferroptosis inducers, such as RSL3 and erastin, due to the increase in YAP1 expression." (PMID 33611811, 2021). "Given the significant prognostic value of YAP1 in ACC, LGG and PAAD, the co-expressed genes with YAP1 in the three types of cancers were analyzed by using LinkedOmics to explore the potential mechanism." (PMID 34257617, 2021). "YAP1, a key molecule in the HIPPO pathway, can translocate into the nucleus upon dephosphorylation where it functions to regulate and maintain cancer stem cell properties as well as the invasion and metastatic ability of CRC cells." (PMID 34395416, 2021). "AURKA and IDH3B are not present in any of the lists of cancer genes, whereas CDK8, MARCH7, YAP1, and YES1 are found among the more than 9000 candidate cancer genes identified by forward genetic screens in mice." (PMID 33427197, 2021). "Following the differential expression of YAP1 in different types of tumors, we firstly employed the GEPIA tool to analyze the prognostic performance of YAP1 in various cancers." (PMID 34257617, 2021). "To explore the internal mechanism for LATS2 involvement in cancers, we investigated the PPI network for LATS2 using the GeneMANIA database and found that LATS2 interacted with YAP1." (PMID 34699318, 2021). "In terms of cancer potential implications, the expression of NEK1 and YAP1 proteins was found to be increased and correlated in several cancers." (PMID 33297404, 2020). "The Hippo TEAD-transcriptional regulators YAP1 and TAZ are central for cell renewal and cancer growth; however, the specific downstream gene networks involved in their activity are not completely understood." (PMID 32193376, 2020). "Previous studies have indicated that YAP1 and TAZ play important roles in cancer cell progression by influencing EMT." (PMID 32678516, 2020). "We subsequently investigated the expression pattern of YAP1 by IHC method in 997 CRC and 70 adjacent normal tissue samples which derive from patients who underwent surgery at Yunnan Cancer Hospital." (PMID 33240680, 2020).
cancer (continued). "Since mutations affecting PP2A subunits are commonly observed in several types of cancer, our observation that certain PP2A complexes can activate YAP1 in the context of ST-mediated transformation suggests that these cancer-associated mutations may also serve, in part, to activate YAP1." (PMID 31913126, 2020). "More interestingly, we find that the cancer-promoting effects of NUSAP1 on GC cell growth, migration, and invasion are mainly mediated by YAP1." (PMID 33489890, 2020). "The precise study of the transcriptional networks regulated downstream of YAP1 and TAZ in somatic stem cells and cancer, particularly in the skin, is hindered by numerous factors." (PMID 32193376, 2020). "Consistently, knockdown of YAP1 by shRNA in GBC-SD and OCUG-1 gallbladder cells significantly inhibited cell proliferation and invasion in vitro and inhibited cancer cell growth in vivo." (PMID 32218280, 2020). "Increasing evidence supports that YAP1 and TAZ are oncogenes in mammalian cells, empowering several of the key attributes of cancer cells such as proliferative advantage, cell invasion and migration, cancer stem cell traits, metastasis and drug resistance." (PMID 32218280, 2020). "AMOTL1, YAP1, and CTGF were silenced, respectively, in GC cell lines followed with the treatment of first-line anti-cancer drugs (Cisplatin and 5-FU)." (PMID 32313226, 2020). "Platelets activate cancer cell survival pathways (e.g. PI3K/AKT and MAPK signaling and RhoA-MYPT1-PP1-mediated YAP1 dephosphorylation) and, thereby, induce anoikis resistance and promote peritoneal and blood-borne metastasis." (PMID 32244723, 2020). "Dysregulation of the Hippo pathway and over-activation of YAP1 and TAZ is common in cancer, and is involved in invasion and metastasis." (PMID 30952872, 2019). "In summary, vitamin C inhibits TNBC metastasis independently of HIF-1α and, likely, by affecting the expression of YAP1 and SYNPO2, two genes in the Hippo pathway which regulate cell mobility and cancer metastasis." (PMID 31817810, 2019). "As the key co-effector, YAP1 and its closely related paralog TAZ act as oncogenes in various cancers." (PMID 31455378, 2019). "Therefore, YAP1 might be an important prognostic marker and a novel target of cancer therapy." (PMID 31613226, 2019). "They control the activity of YAP1 via a LATS kinase independent manner and regulate actin dynamics in cancer cells." (PMID 30934860, 2019). "Targeting to CDCA4, BCL2L2, YAP1, AKT-3 and Cyclin E1, miR-15a has been found to significantly reduce cancer cell survival and aggressiveness." (PMID 30733644, 2019). "Recently, miR-375 has been found significantly downregulated in multiple types of cancer, and suppresses core hallmarks of cancer by targeting several important oncogenes like AEG-1, YAP1, IGF1R and PDK1." (PMID 31737116, 2019). "As effectors of the Hippo signaling cascade, YAP1 and TAZ are transcriptional regulators playing important roles in development, tissue homeostasis and cancer." (PMID 29976931, 2018). "Most components of the Hippo pathway, especially the key downstream effectors YAP1/TAZ, act as crucial regulators in various human cancers." (PMID 28782275, 2018). "Based on the facts above, AMOT promoted YAP1 nuclear translocation and acted as a transcriptional co-factor of the YAP1-TEAD complex to facilitate proliferation of biliary epithelial cells and cancer development of the liver." (PMID 29650031, 2018). "We had previously shown that Yap1 was elevated in cancer stem-like cells from NSCLC and was necessary for their self-renewal and ability to form angiogenic tubules; and these effects of Yap1 were mediated through the induction of Sox2." (PMID 30322398, 2018). "While the role of YAP1/TAZ in organ growth and cancer is well established, the importance of their signaling in angiogenesis and vascular development has emerged only recently." (PMID 29976931, 2018).